TLR4 (toll like receptor 4)
Diseases named in the same sentence as TLR4 in open-access papers (continued):
Sharing a sentence is not in itself a finding about the gene and the disease.
ischemic stroke (continued). "Here, the development of toll-like receptor 4 (TLR4)-binding aptamers for the treatment of ischemic stroke needs to be mentioned." (PMID 40376266, 2025). "Taken together, these findings suggest that the ischemic stroke-induced expression of certain cytokines is influenced by age-dependent changes in their relationship with TLR4." (PMID 40867143, 2025). "HMGB1 expression increases after ischemic stroke and further affects the expression of TLR4, RAGE and other related inflammatory factors, thus reducing the inflammatory response and ultimately protecting against injury." (PMID 40128654, 2025). "In conclusion, our preliminary studies indicate that Evobrutinib can inhibit M1 microglial polarization via the TLR4/MyD88/NF-κB pathway, mitigate neuroinflammation, and potentially serve as a therapeutic agent for ischemic stroke." (PMID 40263985, 2025). "TLR4 is known as a master regulator of inflammatory cytokines and acts as a receptor for DAMPs, which are released during cell death in ischemic stroke." (PMID 40867143, 2025). "Studies in ischemic stroke indicate that neutrophils that lack TLR4 produce less reactive oxygen species, have more phagocytic activity, and are preferentially engulfed by microglia." (PMID 38326029, 2024). "In the context of ischemic stroke, the activation of TLR4 leads to the translocation of NF-κB to the nucleus, promoting the transcription of genes related to inflammation and immune responses." (PMID 38468280, 2024). "Specifically, TLR4 activation contributes to pathological myocardial remodeling and tissue damage after ischemic stroke." (PMID 38961752, 2024). "ApTOLL, a TLR4 modulator aptamer, has demonstrated cerebroprotective effects in a permanent ischemic stroke mouse model, as well as safety and efficacy in early phase clinical trials." (PMID 38931862, 2024). "Meisoindigo, an anti-inflammatory drug, has suppressed TLR4 and NF-κB proteins in ischemic stroke in a dose-dependent manner to alleviate brain damage." (PMID 37915409, 2023). "Polyphenolic natural products, including quercetin, curcumin, resveratrol, baicalin, can regulate microglia polarization by inhibiting TLR4/NF-κB pathway, leading to anti-inflammatory roles in ischemic stroke." (PMID 37361996, 2023). "TLR4 is stimulated by DAMPs in ischemic stroke, which then leads to the activation of NF-κB and AP1 via the MyD88-dependent signaling pathway." (PMID 37915409, 2023). "To summarize, the use of TEAS can suppress the activation of microglia and levels of inflammation, apoptosis, and pyroptosis in neuronal cells following ischemic stroke via suppressing the TLR4/MyD88/NF-κB pathway." (PMID 38273974, 2023). "In conclusion, TEAS can reduce cerebral damage and suppress inflammation, cell death, and microglia activation after ischemic stroke via inhibiting the TLR4/MyD88/NF-κB pathway." (PMID 38273974, 2023). "In ischemic stroke, the TLR4/NF-κB pathway has the ability to trigger the activation of NLRP3 inflammasome, which in turn regulates pyroptosis." (PMID 38273974, 2023). "The elevation of p-Akt/p-mTOR and the reduction of IL-1β, TLR4, p-38, and p-p38 levels have also been observed after curcumin administration in ischemic stroke and were concomitant with curtailed LC-3-II and NLRP3 markers." (PMID 37915409, 2023). "The present study reported the upregulation of TLR4 expression in peripheral blood of ischemic stroke patients from the GEO database and verified that in brain tissue of MCAO mice, which is consistent with the results of previous studies." (PMID 36506580, 2022). "A study observing improvement of neurological function in diabetic rats during ischemic stroke found that SGB can inhibit the Toll-like receptor 4/nuclear factor kappa B signaling pathway and reduce the inflammatory response in the plasma of rats." (PMID 36333751, 2022).
ischemic stroke (continued). "The expression of TLR-4, MyD88, and NF-κB was significantly upregulated in the vehicle group; however, these ischemic stroke-induced changes were markedly reversed by treatment with MFSCE (p < 0.05)." (PMID 35454994, 2022). "It is worth noting that VNS can reduce neuroinflammation after ischemic stroke by inhibiting the TLR4/MyD88/NF-κB pathway in microglia while promoting M2 polarization and inhibiting M1 polarization." (PMID 36211352, 2022). "Ischemic stroke activates toll-like receptor 4 (TLR4) signaling, resulting in proinflammatory polarization of microglia and secondary neuronal damage." (PMID 35745411, 2022). "ROC monofactor analysis demonstrated a good performance of HMOX1, STAT3, CYBB, and TLR4 in the diagnosis of ischemic stroke." (PMID 36506580, 2022). "Recently, it has been shown that TLR4 expression in WBC correlates with poor outcome in ischemic stroke patients." (PMID 34070533, 2021). "TLR4 also mediated hemorrhagic transformation following delayed tPA administration in experimental ischemic stroke." (PMID 33206327, 2021). "Several studies have reported that microglia and MoDM induce neuronal injury in the acute phase of ischemic stroke through a TLR-4-dependent manner and trigger the proinflammatory mediator." (PMID 34094644, 2021). "The mechanisms are associated with suppressing TLR4/NF-κB pathway and NLRP3 inflammasome and enhancing LC3-II and Beclin-1 expressions after ischemic stroke." (PMID 34257822, 2021). "The expression of three other ferroptosis-related biomarkers, PTGS2, MAP1LC3B, and TLR4, was all upregulated in ischemic stroke patients vs. normal control in the GSE16561 (all p < 0.05) and GSE140275 datasets (all p < 0.05)." (PMID 34707562, 2021). "Collectively, cAMP/PKA, IκB/NF-κB, and Caspase 3 signaling pathways mediated by TLR4 and C5aR1 were identified to be essential for the inflammatory response and cell apoptosis in ischemic stroke of MCAO/R-exposed rats." (PMID 33633530, 2021). "Toll-like receptor 4 (TLR4), a membrane receptor for damage-associated molecular patterns, is primarily involved in the inflammation associated with ischemic stroke." (PMID 33557283, 2021). "Chimeric mice with microglia expressing TLR4 and neutrophils expressing non-TLR4 had neuroprotection during ischemic stroke, as modeled with permanent middle cerebral artery occlusion." (PMID 34576137, 2021). "ROC monofactor analysis demonstrated a good performance of MAP1LC3B, PTGS2, and TLR4 in the diagnosis of ischemic stroke." (PMID 34707562, 2021). "By constructing a random forest model and performing ROC monofactor analysis, we identified three ferroptosis-related biomarkers, namely, MAP1LC3B, PTGS2, and TLR4, for ischemic stroke." (PMID 34707562, 2021). "Collectively, these results strongly suggested that the TLR4/NF-κB/MAPK signalling pathway was involved in the anti-inflammatory effects of PTH in ischaemic stroke." (PMID 34196587, 2021). "As a result, the accuracy of MAP1LC3B, PTGS2, and TLR4 in the diagnosis of ischemic stroke was 67.74, 72.86, and 74.25, respectively, in the GSE16561 dataset." (PMID 34707562, 2021). "In vitro experiments further verified that hesperidin plays a neuroprotective role by inhibiting the TLR4-NF-κB pathway, thus providing new targets and strategies for neuroprotection and nerve repair after ischemic stroke." (PMID 34956584, 2021). "Peroxiredoxins (Prxs) are a family of thioredoxin peroxidases that activate the Toll-like receptor 4 in immune cells and initiate neuro-inflammation after ischemic stroke." (PMID 32317937, 2020). "Previously, it has been shown that Prx1, Prx2, Prx5 and Prx6 are potent DAMPs in ischemic stroke, with TLR4 being their main recognition receptor." (PMID 32751232, 2020). "Meanwhile, melatonin treatment was found to enhance its therapeutic effect on ischemic stroke through the TLR4/NF-κB pathway." (PMID 33013286, 2020).
ischemic stroke (continued). "Studies have indicated that microglia damage neurons in a TLR-4-dependent manner in early ischemic stroke, while inhibition of microglia activation reduces brain infarction and blood–brain barrier (BBB) leakage." (PMID 32466277, 2020). "Toll-like receptor 4 (TLR4) and nuclear factor kappa B (NF-κB) have been identified as the key molecules leading to microglia and astrocyte activation following ischemic stroke." (PMID 32917229, 2020). "On the other hand, although bacterial LPS is the stereotype ligand of TLR4, this receptor also has been shown to be essential in the sterile inflammation occurring both after hemorrhagic stroke and in ischemic stroke." (PMID 31791382, 2019). "Release of inflammatory proteins further exacerbate ischemic stroke injury by several mechanisms, such as activation of Toll like receptor (TLR-4) on glial cells stimulates stress kinases like (JNK and P38-MAPK)." (PMID 31798514, 2019). "Our study indicates that microglial GPR30 plays a key role in the TLR4-mediated inflammatory response and in the acute neuroprotective effects of estrogen after ischemic stroke, which enhances our comprehension of GPR30’s function in the CNS." (PMID 30001721, 2018). "It concluded that tissue kallikrein protects against ischemic stroke through antioxidation and anti-inflammation by suppressing TLR4/NF-κB signaling pathway in rats." (PMID 29922218, 2018). "TLR4 activation is an important mechanism in ischemic stroke, given that ischemia-induced neuronal damage triggers the release of endogenous ligands for TLR4." (PMID 27143001, 2016). "Brea and coworkers have analyzed the TLR2 and TLR4 expression at a protein level by flowcytometry in blood samples from patients with ischemic stroke (at 24-h, 72-h and 7-day time points), as well as in healthy controls subjects." (PMID 27040385, 2016). "In this study, we investigated the roles of the TLR4 signalling pathway in IP to exert neuroprotection following ischemic stroke in vivo and in vitro." (PMID 26086415, 2015). "Neutralizing TLR4 at the time of intracerebral hemorrhage and ischemic stroke provides neuroprotection." (PMID 24223475, 2013). "The rising blood levels of LBP and sCD14 may serve as a compensatory mechanism to prevent excessive TLR4 stimulation and to limit systemic inflammation in patients with ischemic stroke." (PMID 39859200, 2025). "In addition, Tlr4 expression was influenced by aging and by an interaction between ischemic stroke and aging." (PMID 40867143, 2025). "Inhibiting TLR4 has been shown to effectively reduce inflammation after an ischemic stroke." (PMID 40791737, 2025). "Notably, ZEB1 has been shown to interact with GPR30, modulating inflammatory responses in ischemic stroke via TLR4/NF-κB pathway inhibition." (PMID 40726812, 2025). "Interestingly, WEU administered for 7 d obviously attenuated the protein expression of TLR4, NF-κB and p-p38 compared to unadministered ischemic stroke mice." (PMID 40004043, 2025). "Moreover, a previous study has reported that Dioscin suppresses ischemic stroke‐induced inflammation by TLR4/MyD88/NF‐κB signal pathway in a rat model." (PMID 38775678, 2024). "TLR4 is an important mediator in neuroinflammatory-related disease that is primarily expressed by microglia and has been demonstrated to have a role in traumatic brain injury and ischemic stroke." (PMID 39881804, 2024). "Additionally, VNS can increase ACh levels in the rat brain, thereby activating α7nAChR in microglia after ischemic stroke, which inhibits the peripheral inflammatory response in part through the TLR4/NF-κB pathway." (PMID 39881804, 2024). "Moreover, TLR4-induced neuroinflammation through downstream NF-κB signaling activation is positively correlated with ischemic stroke severity." (PMID 39391701, 2024).
ischemic stroke (continued). "Recent research has demonstrated that mesencephalic astrocyte derived neurotrophic factor (MANF) inhibits the production of proinflammatory factors and relies on the TLR4/MyD88/NF-B pathway to maintain the integrity of the blood-brain barrier in a geriatric mouse model following an ischemic stroke." (PMID 38020537, 2023). "Hence, the TLR4/MyD88/NF-κB signaling pathway has the ability to control inflammation in neuronal cells following ischemic stroke." (PMID 38273974, 2023). "According to a study using a rat model, inhibition of the TLR4/NF-κB pathway or promotion of TLR4 degradation could prevent microglia-induced neuroinflammation and alleviate post-ischemic stroke or reperfusion injury." (PMID 36979506, 2023). "Therefore, TLR4/NF‐kB pathway in the ischemic stroke rat models after transplantation was investigated." (PMID 35695696, 2022). "TLR4 signaling-mediated neuroinflammation leads to secondary brain damage in ischemic stroke." (PMID 36408278, 2022). "TRAF6 has also been linked to the toll-like receptor 4 (TLR4) signaling pathway through its interaction and activation of nuclear factor-kappa B (NF-κB), thereby participating in the inflammatory response after an ischemic stroke." (PMID 34440890, 2021). "Moreover, the random forest model suggested three ferroptosis-related biomarkers, namely, PTGS2, MAP1LC3B, and TLR4, for ischemic stroke." (PMID 34707562, 2021). "Finally, the non-cooperatively expressed MIF was removed, and PTGS2, MAP1LC3B, and TLR4 were further selected as ferroptosis-related biomarkers for ischemic stroke." (PMID 34707562, 2021). "Furthermore, our data proved that DADLE repressed I/R-induced TLR4 expression, which led to downregulation of cerebral inflammation after ischemic stroke." (PMID 33628116, 2021). "An initiation of the Tlr signaling can occur through transfer of bacterial LPS, particularly as plasma levels of LPS are elevated in ischemic stroke, by Lbp to a receptor complex that localizes on microglia and includes Tlrs (the most known Tlr4) and co-receptor CD14." (PMID 34944656, 2021). "As TLR4 can aggravate inflammatory damage, many studies are based on directly inhibiting TLR4 expression or related signaling pathways to find suitable drugs to protect against the effects of ischemic stroke." (PMID 33893248, 2021). "Actually, a previous study had reported that MAP1LC3B, PTGS2, and TLR4 may play a vital role in ischemic stroke or served as biomarkers for ischemic stroke and other diseases." (PMID 34707562, 2021). "By the bioinformatic analysis, three ferroptosis-related biomarkers are found as potential diagnostic biomarkers for ischemic stroke, namely, PTGS2, MAP1LC3B, and TLR4, which are upregulated in ischemic stroke and provide more evidence about the important role of ferroptosis." (PMID 35264947, 2021). "In conclusion, the current findings indicate that CSO treatment can alleviate ischemic stroke injury via reducing inflammatory microglia and astrocytic activation, which was correlated to the inhibition of TLR4/NF-κB pathway and the reduction of A1 type neurotoxic astrocyte activation." (PMID 32917229, 2020). "Since inflammatory responses contribute to hypoxic injury and importance of TLR4 in inflammatory mechanisms has been well recognized, blocking TLR4/MyD88 signaling pathway may be a potentially neuroprotective therapeutic strategy for ischemic stroke." (PMID 29234386, 2017). "Stimulation of TLR4/MyD88 signaling is important for inflammatory responses in ischemic stroke." (PMID 29234386, 2017). "However, ischemic stroke increases expression of the TLR4 not only in microglia but also in astrocytes and to a lesser extent in neurons." (PMID 28245599, 2017). "TLR4 is the most widely investigated pattern recognition receptor in ischemic stroke." (PMID 27716839, 2016).
ischemic stroke (continued). "Furthermore, TLR4-mediated signaling pathways activate the downstream targets JNK and p38 mitogen-activated protein kinase (MAPK), which in turn induce TLR4 upregulation, amplifying TLR4/NF-κB-mediated signaling and exacerbating infarct expansion in the acute stage of ischemic stroke." (PMID 39391701, 2024). "Inhibition of TLR4 may play a role in reducing inflammation in ischemic stroke." (PMID 38154101, 2023). "Therefore, TLR4, is a potential therapeutic target to improve management of ischemic stroke." (PMID 36879557, 2023). "Hence, blocking the TLR4/MyD88/NF-κB pathway is a crucial approach to diminish neuronal cell inflammation, while also suppressing apoptosis and pyroptosis levels, ultimately easing the impact of ischemic injury in cases of ischemic stroke." (PMID 38273974, 2023). "This study was to explore whether transcutaneous electrical acupoint stimulation (TEAS) treatment could mediate inflammation, apoptosis, and pyroptosis of neuronal cells and microglia activation through the TLR4/MyD88/NF-κB pathway in the early stage of ischemic stroke." (PMID 38273974, 2023). "ApTOLL, a DNA aptamer (ssDNA), is a Toll-like receptor 4 (TLR4) antagonist, a receptor that is involved in innate immune responses but also responds to tissue damage-associated molecular patterns (DAMPs), and therefore it is directly involved in a large number of diseases such as ischemic stroke." (PMID 36908619, 2023). "Notably, it was reported that miR-140-5p could nullify the high glucose-induced inflammation and apoptosis in renal tubular cells and mediate neuroprotection in ischemic strokes via exploitation of TLR4/NF-κB pathway." (PMID 36277770, 2022). "Interestingly, the expression of PTGS2, MAP1LC3B, and TLR4 was upregulated in ischemic stroke." (PMID 34707562, 2021). "In ischemic stroke, pre-conditioning with LPS reduces infarct volume, decreases the infiltration of peripheral immune cells into the brain parenchyma, attenuates microglia reactivity and increases the expression of anti-inflammatory cytokines via TLR4 signaling." (PMID 32116567, 2020). "Experimental in vivo studies demonstrating a detrimental role of microglia in ischemic stroke used essentially indirect approaches such as depletion of genes mediating signaling pathways not only in microglia but also in other brain and immune peripheral cells, such as TLR4." (PMID 28245599, 2017). "Notably, it has been reported that HMGB1 released from damaged tissue may function as an endogenous agonist of TLR4 that aggravates ischemic brain damage in an ischemic stroke model." (PMID 28646881, 2017). "Similarly, it is reasonable propose that activated macrophages induced by inflammatory DAMPs, such as Prx1, 2 and 4, probably provide a novel cellular model suitable for screening novel anti-inflammatory neuroprotants that inhibit Prxs/TLR4 signaling pathway in ischemic stroke." (PMID 27716839, 2016). "Hence, microglial TLR4 may be as a potential therapeutic target to inhibit microglial activation for ischemic stroke treatment." (PMID 26086415, 2015). "In ischemic stroke (IS), eCIRP promotes neutrophil extracellular trap (NET) formation and increases microglial activity via the Toll-like receptor 4 (TLR4) pathway." (PMID 41750206, 2026). "It modulates neuroinflammation via the mitogen-activated protein kinase (MAPK) and Toll-Like Receptor 4 (TLR4) signalling pathways, potentially reducing neuroinflammatory proteins and improving ischaemic stroke outcomes." (PMID 39337520, 2024). "Pinocembrin is a TLR4 inhibitor that has been approved by the Chinese Food and Drug Administration (CFDA) as a therapeutic agent for ischaemic stroke and is currently in phase II clinical trials." (PMID 35393774, 2022). "The presence of several TLRs has been reported in the brain, both in glial and neuronal cells, and recent studies have reported the pathological roles of TLR2, TLR4 and TLR8 in ischemic stroke-induced brain injury." (PMID 25886362, 2015).